EGFR (epidermal growth factor receptor)
Diseases named in the same sentence as EGFR in open-access papers (continued):
Sharing a sentence is not in itself a finding about the gene and the disease.
tumor (continued). "Our experimental results showed that after drug withdrawal, microvascular densities in tumor tissues in the bevacizumab, recombinant human endostatin and combined drug groups, containing antiangiogenic drugs, were lower than those of control animals and the EGFR‐TKI group alone." (PMID 34855286, 2022). "Evolution of tumor volume prior and after calibration was compared to the experimental data used for calibration for each of the four scenarios: EGFR mutation with or without gefitinib, EGFR and PIK3CA mutation with or without gefitinib." (PMID 35796890, 2022). "NGS analysis of 33 EGFR-wildtype tumors revealed two rare EGFR mutations (H773Q in two tumors from one patient and A289V in one tumor from other patient), which could not be detected using the cobas® EGFR mutation test v2." (PMID 35740676, 2022). "With the help of EGFR targeting, the nanoengagers provided a robust chemoimmunotherapy platform that could recruit and activate NK cells to eliminate tumors and release cytotoxic drugs for tumor chemotherapy." (PMID 35664074, 2022). "Overall, 41.4% of patients had a tumor harboring a major uncommon mutation, 22.3% had an exon 20 insertion (of which only 18.4% were fully informative), 20.3% had a T790M mutation (predominantly in the EGFR TKI-pretreated patients), and 15.9% had other uncommon EGFR mutations." (PMID 35574304, 2022). "Moreover, the previous report showed that the EGFR/AKT signal could promote tumor cell proliferation through regulating immune cells, such as CD8+ T cells recruited by CXC-chemokine ligand 10 (CXCL10)." (PMID 35237300, 2022). "In addition, knockdown of EGFR or overexpression of miR-134-5p could reverse the tumor-promoting effects of circZNF609 in LSCC." (PMID 35236250, 2022). "In summary, we highlight the profound effect of pY-Gel supramolecular hydrogel on skin damage repair and demonstrate that GMSCs-CM may promote skin cell proliferation and migration through activation of the EGFR/STAT3 signaling pathway, which ultimately promotes skin injury repair." (PMID 36231051, 2022). "Previous evidence showed that OXPHOS upregulation through inhibition of the EGFR pathway is associated with an increase in intracellular ATP, and a decrease in PKM2 phosphorylation, stimulation of catabolism, and these mechanisms have an impact on tumor cell proliferation and protein synthesis." (PMID 35337178, 2022). "Although EGF : EGFR interaction is essential for normal maintenance and renewal of epithelial cell populations, the overexpression and hyperactivation of EGFR contributes to tumor progression, rendering it an important biomarker and target for anticancer therapeutics." (PMID 36591314, 2022). "Thus, it appeared that LIGHT expression could synergize with BATs to support T-cell proliferation and impart greater tumor regressions than anti-EGFR alone." (PMID 35177811, 2022). "Additionally, genes in the Hedgehog, Notch, TGFβ, WNT signaling, and EGFR signaling pathways, which are related to malignant progression of tumor, were selected for further investigating whether there were notable interactions between cell clusters." (PMID 35620271, 2022). "However, genetic features such as epidermal growth factor receptor mutation status, anaplastic lymphoma kinase mutation status, programmed death ligand 1 expression level, and tumor mutation burden were not recorded in the database." (PMID 36439488, 2022).
tumor (continued). "Non-invasive molecular imaging agents, such as anti-EGFR monoclonal antibodies conjugated MR constrast, Tc-99m 8B6 Nanobody, F-18 Affibody protein, C-11 erlotinib, Lu-177 nimotuzumab, and C-11 4-N-(3-bromoanilino)-6, 7-dimethoxyquinazoline, have been developed for evaluating EGFR status of tumor." (PMID 35120180, 2022). "MiR-323a-3p, a tumor suppressor, could target both ErbB3 and EGFR directly." (PMID 35319011, 2022). "Therefore, increases in the internalization efficiency of EGFR-targeting ADCs may enhance their anti-tumor activities." (PMID 35798841, 2022). "A high EGF amount plus EGFR overexpression could create conditions for tumor growth, even without specific EGFR mutations." (PMID 36146635, 2022). "Third, unlike wild-type EGFR patients, EGFR mutations affect anti-tumor immune responses by modulating factors that may be associated with tumor microenvironmental status (for instance, tumor-infiltrating lymphocytes, regulatory T cells, and exosome CD73)." (PMID 35799785, 2022). "Also, high tumor uptake of 11C-erlotinib or 18F-afatinib was found to be associated with response to treatments using the respective TKI, highlighting the predictive value of EGFR TKI PET." (PMID 35453931, 2022). "However, during chronic inflammation, it may recruit and transactivate epidermal growth factor receptor (EGFR) in skin cells, permitting their expansion and migration, and provoke general tumor outgrowth." (PMID 36298472, 2022). "In a preclinical study, ONO-7475 (AXL/MER inhibitor) plus osimertinib overtly reduced tumor size and suppressed tumor growth compared to osimertinib alone, or combination therapy after acquisition of osimertinib resistance in AXL-overexpressing EGFR-mutated NSCLC xenograft models." (PMID 35311091, 2022). "PAK1 confers TKI resistance to tumor cells, whether it is in EGFR-mutant or EGFR wild-type cells." (PMID 36230657, 2022). "In addition, we queried the phosphorylation status of the proteins and found that mTOR and MAP2K1 showed consistent increases (p<0.05) in dephosphorylation, while EGFR was consistently hyper-phosphorylated (p<0.05) in higher tumor grades (normal, grades I~III)." (PMID 35655775, 2022). "We next plan to link A1 NPs with some tumor targeting antibodies, such as anti-EGFR, anti-PMSA, anti-VEGF antibodies to construct tumor-targeted theranostic agents, as combination of both passive and active targeting approaches might further improve theranostic effect." (PMID 35305654, 2022). "In a phase II/III randomized, double-blind study testing stage IV NSCLC patients lacking an EGFR mutation while also expressing ≥ 50% of MUC1 on tumor cell surface, 222 patients received standard first-line chemotherapy in combination and without combination of TG4010 vaccine." (PMID 36059606, 2022). "Tumor uptake (%ID/g; percentage injected dose per gram of organ or tissue) in AB-36, AB-37 and AB-53 groups, but not the AB-39, was significantly higher in the non-blocking group compared to the blocking group, indicating the presence of EGFR expression in those tissues." (PMID 36357495, 2022). "Therefore, we considered EGFR as an ideal target to draw the BsAb to the tumor, and one that could be exploited for surface binding that was not dependent on downstream signaling for efficacy." (PMID 35177811, 2022). "In addition to EGFR abundance, other factors in the microenvironment of the tumor may predict the tumor-to-lung contrast." (PMID 35890095, 2022). "Moreover, EGFR overexpression, caused by the USP48 and BRAF genes, could subsequently enhance cell proliferation and tumor growth in PAs." (PMID 35454025, 2022). "EGFR and its ligands (e.g., EGF, transforming growth factor-alpha) are overexpressed in up to 90% of head and neck cancer patients, are further induced by standard of care external beam radiation and DNA damaging agents, and are strongly linked to tumor progression." (PMID 35569509, 2022).
tumor (continued). "In samples in which the tumor invaded beyond the serosa, the association with KRAS Q61 mutation decreased: OR = 1.630 (95% CI = [0.444, 5.984]) and RR2 = 1.395 (95% CI = [0.961, 1.827]), but the association with EGFR mutation presence increased RR2 = 3.003 (95% CI = [2.901, 3.105])." (PMID 35681771, 2022). "The reason for this is to provide the appropriate treatment by investigating whether the tumor expresses the epidermal growth factor receptor (EGFR), anaplastic lymphoma kinase (ALK), proto-oncogene 1 (ROS-1), proto-oncogene B-Raf (BRAF), and programmed death-ligand 1 (PD-L1)." (PMID 35329255, 2022). "Alternatively, classification of EpCAM+EGFR+ events as tumor cells could be unjustified." (PMID 36613466, 2022). "Therefore, the specific intervention of PDLIM5 expression may relieve the inhibitory effect of AMPK activation on mTOR under stress state, and then affect cell proliferation, accelerate cell apoptosis, and improve drug sensitivity of tumor cells to EGFR-TKIS." (PMID 34964410, 2022). "Furthermore, stronger EGFR/HER2/Akt signals were observed in the PLC/PRF-5LL-37 xenograft tumor." (PMID 35039485, 2022). "It has been reported that the overexpression of Erb-B2 Receptor Tyrosine Kinase 2 (ERBB2), mutations of EGFR/PI3K pathway, or the loss of Phosphatase and Tensin Homolog (PTEN), as well as mutations or amplification of AKT itself can result in increased PI3K-AKT signaling in tumor cells." (PMID 36434592, 2022). "In addition to regulating tumor growth, the EGFR pathway also regulates tumor microenvironment." (PMID 36443704, 2022). "Thus, tumors without evidence of alterations at the EGFR locus may still harbor sub-populations of tumor cells expressing both EGFR and CD73." (PMID 35973991, 2022). "Therefore, future investigations could contribute to not only canine, but also human EGFR/HER2-positive tumor treatment." (PMID 36432687, 2022). "With the use of AI algorithms, EGFR status could be predicted by combining clinical and CT features such as smoke history, tumor size, bubble-like lucency, enhancement pattern, presence of pleural retraction, and thickened adjacent bronchovascular bundles (AUC = 0.778)." (PMID 36359485, 2022). "Besides, MET amplification and EGFR C797S were detected only in the tumor tissues." (PMID 35646096, 2022). "The high EGFR expression could be closely related to tumor metastasis in LUAD." (PMID 36291859, 2022). "In addition, the combinatory use of honokiol and cetuximab, a chimeric antibody against EGFR, could effectively inhibit the xenograft tumor formation." (PMID 35269825, 2022). "Moreover, EGFR is often highly overexpressed on human tumor cells." (PMID 35035479, 2022). "Interestingly, the EGFR signaling pathway is related to tumor dormancy and drug resistance." (PMID 35462906, 2022). "PIM1 might act upstream of cluster 27, which in turn is upregulated in EGFR WT tumor samples." (PMID 35360705, 2022). "One hypothesis arising from this observation is that certain co-occurring alterations present in an EGFR-mutant tumor could modulate sensitivity to EGFR TKI treatment and explain, in part, the variable magnitude and duration of antitumor treatment responses in patients." (PMID 35579943, 2022). "The aberrant constitutive endocytosis of activated EGFR mutants not only confers enhanced signalling activity, but also promotes their colocalisation and association with c-SRC, thereby amplifying signalling dysregulation and contributing to tumour progression." (PMID 35158954, 2022). "Researchers analyzed a total of 39 pairs of normal and tumor lung tissue samples (20 cases with EGFR mutations), and the TCR diversity index was found to be significantly elevated, while the clonal expansion of T cells in EGFR mutant tumors was compared with that in EGFR wild-type tumors." (PMID 35935943, 2022). "Therefore, it is likely that EGFR inhibitors might only be of interest in preliminary stages to prevent the spreading of metastases from the primary tumour." (PMID 36380366, 2022).
tumor (continued). "However, with activating mutations in the EGFR kinase domain, activation occurs in the absence of a ligand, leading to tumor cell proliferation and growth." (PMID 36313723, 2022). "In addition to evaluating the EGFR-TKI treatment efficacy and the emergence of resistance mechanisms, the use of the ddPCR method for EGFR mutation detection is proven to be valuable in predicting tumor metastasis and patient outcomes." (PMID 36232650, 2022). "Moreover, genes associated with tumor proliferation, metastasis, and progression pathways, including Hedgehog, Notch, TGFβ, WNT, and EGFR, were selected to explore whether significant interaction was observed between cell subgroups." (PMID 35935973, 2022). "However, PEGylated SSNs with complexed anti-EGFR siRNA showed much slower tumour growth rate, exerting significantly high tumour inhibitory effects with the average tumour volume of ~726.46 mm3 (almost 60% reduction), compared to the control and empty NPs treatment groups." (PMID 36412852, 2022). "Since these compounds possess higher affinity than the natural kinase substrate, ATP for the ATP-binding pocket in EGFR, they competitively inhibit the tyrosine kinase activity of the mutant receptor, thus blocking downstream signalling which in turn leads to inhibition of tumour cell growth." (PMID 35055414, 2022). "The arachidonic acid metabolic chain may be inhibited by EGFR-TKIs or PD-1/PD-L1 inhibitors, making it unable to produce pro-inflammatory and pro-tumor substances (such as eicosanoids) through key enzymes in the arachidonic acid metabolic network, thus causing a raise of the arachidonic acid." (PMID 36034789, 2022). "Examples of cytokine-receptor pairs implicated in MSC tumour tropism are SDF-1 & C-X-C motif chemokine receptor-4 (CXCR4), VEGF & VEGFR, MCP-1 & C-C motif chemokine receptor (CCR2), epidermal growth factor (EGF) & EGFR, and hepatocyte growth factor (HGF) & c-Met." (PMID 35103937, 2022). "Thus, EGFR has a relevant role in NSCLC tumor progression and treatment resistance." (PMID 35455052, 2022). "In addition, a tumor xenograft mouse model suggested that tumor-derived MVs could transfer EGFR to tumor blood vessels and contribute to tumor growth and angiogenesis." (PMID 35158999, 2022). "Therefore, inhibiting the EGFR expression can prove beneficial in controlling tumor progression." (PMID 35769445, 2022). "Moreover, the crosstalk of EGFR with the tumor microenvironment (TME) could affect the immunity to cancer." (PMID 36619616, 2022). "However, because EGFR is also expressed in non-tumor organs, such as the liver, the diagnosis of hepatic metastasis using EGFR-based molecular imaging remains unsatisfactory, even though the incidence of HNSCC metastasis to liver is relatively low compared to other types of cancer." (PMID 35962347, 2022). "Interestingly, we observed that 92% of RBM10 alterations present in our EGFR-mutant tumor data set did not co-occur with a known EGFR TKI resistance–associated mutation such as EGFR T790M or C797S or MET gene amplification." (PMID 35579943, 2022). "Besides the newly-identified EGFR, the tumor growth and metastasis suppression effects of FBXW2 in PCa might be induced through other potential substrates of FBXW2, like SKP2." (PMID 35499593, 2022). "Thus, they have less demand for EGFR-TKIs compared to low metabolic tumor cells." (PMID 35800046, 2022). "Moreover, they observed that EGFR was expressed in metastatic circulating tumor cells." (PMID 36228719, 2022). "Furthermore, Choi and co-workers demonstrated that binding EGFR-targeting Abs to gemcitabine (Gem) encapsulated nanoplatforms could effectively inhibit tumor growth." (PMID 36096856, 2022). "Also, the intestinal flora may promote serrated lesions through EGFR signaling, the induction of cellular proliferation, the activation of a tumor immunosuppressive microenvironment, and the induction of an inflammatory response." (PMID 35727391, 2022).
tumor (continued). "Moreover, EGFR activity was positively correlated with tumor progression." (PMID 35186080, 2022). "However, the distribution of high and low B7-H3 expression was not related to age, sex, tumor size, staging, or EGFR mutation patterns." (PMID 36555714, 2022). "Patients with mutated EGFR may be misdiagnosed as having no mutations or may be unable to detect major mutations in mixed tumor clones by nucleotide sequencing." (PMID 36457515, 2022). "Therefore, as compared to anti-EGFR therapy alone, which had a similar impact on tumor volume, that BATs treatment established an anti-tumor immune response that could reject tumor rechallenge is critical to improving overall and disease-free survival." (PMID 35177811, 2022). "Cetuximab, a recombinant human-murine chimeric monoclonal antibody, binds explicitly to EGFR on the cell surface, internalizes it, and blocks the downstream signal transduction leading to inhibition of tumor cell proliferation, invasion, metastasis, angiogenesis, and promoting tumor cell apoptosis." (PMID 35663647, 2022). "Therefore, the sensitivity of tumour cells to EGFR-TKIs is speculated to improve in NSCLC-resistant cells by affecting the effect of autophagy on epidermal growth factor receptor (EGFR) and reducing the resistance of EGFR mutant NSCLC cells." (PMID 36154921, 2022). "For example, growth factor receptors may be overexpressed and accessible at the membrane of tumor cells, so antibodies targeting growth factor receptors may be used, such as the anti-epidermal growth factor receptor (EGFR) antibody (cetuximab) or trastuzumab (anti-ERBB2, Herceptin®)." (PMID 35626059, 2022). "EGFR and MET belong to members of the RTK family, and MET, the tyrosine kinase transmembrane receptor for MET, is a protein product encoded by the c-MET proto oncogene that has been of interest in the clinic as a potential therapeutic target in multiple tumor types." (PMID 35227278, 2022). "EGFR is a tumor driver factor whose overexpression may promote tumor cell proliferation." (PMID 36304985, 2022). "EGFR-mediated EMT may have various repercussions on tumor progression." (PMID 36076232, 2022). "Given the observations of possible suppression of the anti-tumour immune response in mice null for miR-21, targeted delivery to the tumour may be required, for example, by coupling a miR-21 antisense sequence to an EGFR aptamer, as described by Shu and colleagues." (PMID 35821197, 2022). "In addition, another level oftumor selectivity may be achieved by tagging these QDs with tumor-specificligands, such as folic acid, anti-Her2, or anti-EGFR antibodies." (PMID 35104130, 2022). "Resistance to anti-EGFR monotherapy can arise due to different regulatory mechanisms that operate at the level of EGFR and its ligands, alternative parallel signaling pathways in the cells as well as the cross-talk between EGFR expressing cells and the tumor microenvironment." (PMID 35154483, 2022). "Several researchers considered that EGFR-TKIs could accelerate the glucose uptake of tumor cells." (PMID 35800046, 2022). "Additionally, eBAT has been shown to exert cytotoxicity on head and neck squamous cell carcinoma and triple-negative breast cancer cells, both overexpressing EGFR and uPAR on the cell surface, and inhibit tumor growth when neck squamous cell carcinomas were implanted in nude mice." (PMID 35158766, 2022).